GDF5-AS1 (GDF5 antisense RNA 1)
Synonyms: formerly GDF5OS
Gene: Long non-coding RNA gene on chromosome 20 (35,433,029 to 35,435,450, forward strand). Ensembl gene ENSG00000204183.
Subcellular location: Mitochondrion